POLE (DNA polymerase epsilon, catalytic subunit)
Diseases named in the same sentence as POLE in open-access papers (continued):
Sharing a sentence is not in itself a finding about the gene and the disease.
colorectal cancer (continued). "In sum, while POLE mutations seem uncommon, such mutations may well prove important as the role of immune checkpoint inhibitors evolves in colorectal cancer." (PMID 28492495, 2017). "This is the first study to functionally analyze a POLE genetic variant outside the exonuclease domain and widens the spectrum of genetic changes in this DNA polymerase that could lead to colorectal cancer predisposition." (PMID 28423643, 2017). "PPAP-associated colorectal cancers where POLE is the causative gene may exhibit MSI-H." (PMID 34185173, 2021). "As mutation of the tumour suppressor genes PTEN and APC are well recognized as early, if not initiating, events in the pathogenesis of endometrial and colorectal cancers, respectively, we specifically examined whether somatic variants in these genes varied according to tumour POLE mutation status." (PMID 29604063, 2018). "While heterozygous GVs in POLE and PMS2 cause polymerase proofreading-associated polyposis or hereditary non-polyposis colorectal cancer, respectively, predisposing to colorectal cancer, they have also been linked to glioma risk, in line with our data." (PMID 41546701, 2026). "Mutations in the exonuclease domains of the POLE and POLD1 genes (present in ~1–2% and <1% of colorectal cancers, respectively) lead to a hypermutated phenotype characterized by defective DNA proofreading." (PMID 40805233, 2025). "P5 had the POLE T278K mutation, which was previously linked to ultramutated features and MSI‐high status in both EC and colorectal cancer." (PMID 39865420, 2025). "Two main acquired mutator phenotypes are well described in colorectal cancers, MSI caused by defective DNA mismatch repair and aberrant polymerase proofreading caused by POLE mutations." (PMID 39751654, 2025). "Both POLE and POLD1 mutations are incorporated into clinical guidelines for the management of endometrial and colorectal cancers." (PMID 41301688, 2025). "High levels of SBS10 related to defects in POLE were observed in 22 colorectal carcinomas and three uterine corpus endometrial carcinomas." (PMID 40778578, 2025). "In colorectal cancer, the primary mutation associated with SBS 10b (TCG>TTG) comprised 36.1% of POLE variants." (PMID 38282550, 2024). "Germline mutations in the POLE and POLD1 genes, coding for DNA polymerases ε and δ, were described to be associated mainly with an increased risk of polyposis and colorectal cancer." (PMID 39684352, 2024). "In 2016, the team at the University of Oxford discovered that alterations in POLE proofreading are ideal biomarkers for recurrence in early-stage colorectal cancer, and these patients have the potential to avoid adjuvant chemotherapy." (PMID 37907475, 2023). "In the 10 families carrying POLE/POLD1 variants, other tumors were colorectal cancer (4/10, 40%), breast cancer (2/10, 20%), uterus cancer (1/10, 10%), prostate cancer (1/10, 10%), and small cell lung cancer (1/10, 10%)." (PMID 37990341, 2023). "It has been over a decade since the initial identification of exonuclease domain mutations in the genes encoding the catalytic subunits of replication DNA polymerases ε and δ (POLE and POLD1) in tumors from highly mutated endometrial and colorectal cancers." (PMID 37388540, 2023). "Further prospective studies are needed to reproduce the effect of checkpoint inhibition on POLE-mutant colorectal cancers in larger clinical settings." (PMID 37239414, 2023). "We also found 7.4% of NCVs were associated with POLE signatures (SBS61, SBS62, and SBS10a frequently present in colorectal cancers) and 1.4% were associated with APOBEC signatures (SBS2 and SBS13)." (PMID 36808133, 2023). "In some families with susceptibility to colorectal cancer (OMIM #615083), a heterozygous missense mutation in a highly conserved residue (L424V) in the proofreading exonuclease domain of POLE was identified." (PMID 37175782, 2023).
colorectal cancer (continued). "It is also reported that specific heterozygous germline mutations in the proofreading exonuclease-coding region and splicing sequences of POLE and POLD1 are associated with oligo-adenomatous polyposis, early-onset colorectal cancer and endometrial cancer." (PMID 37175782, 2023). "Pathogenic germline variants in the DNA polymerase genes POLE and POLD1 cause polymerase proofreading-associated polyposis, a dominantly inherited disorder with increased risk of colorectal carcinomas and other tumors." (PMID 37990341, 2023). "Consistent with the high prevalence of MSI and POLE subtype, BRAF/PIK3CA double mutant colorectal cancers in TCGA had a high Tumor Mutation Burden (TMB) above 200 in 86.4% of cases." (PMID 36079062, 2022). "Pathogenic variants in POLE and POLD1 cause PPAP syndrome (polymerase proofreading-associated polyposis), where there is an increased risk of developing colorectal cancer." (PMID 36232851, 2022). "Current biomarkers for anti-PD1 in colorectal cancer, MSI/MSS, TMB, PDL1, and POLE/POLD1 mutation, share the same notion that anti-PD1 resistance is dominantly caused by one homogenous factor of an insufficient amount of CD8+ T-cell infiltration." (PMID 34594218, 2021). "POLE-driven tumors are relatively common in endometrial and colorectal cancer, and their presence is increasingly recognized in ovarian cancer (OC) of endometrioid type." (PMID 34158040, 2021). "The differential mutation spectrum clustering of P286R from V411L mutants was also evident in an additional 32 POLE mutant colorectal cancer samples with WGS, WXS and target capture sequencing data, confirming the differences observed in the WGS samples." (PMID 32012149, 2020). "There is a single case of colorectal cancer (CRC) in The Cancer GenomeAtlas (TCGA) project carrying the POLE S459F mutation and a nonsensemutation at codon 150 of the POLE gene, which was thought to inactivatethe second allele." (PMID 33001133, 2020). "Pathogenic variants affecting the exonuclease domains of POLE and POLD1 are associated with polyposis and colorectal cancer." (PMID 30827058, 2019). "Accordingly, our results suggest that the use of tumour mutation burden as a prognostic and predictive marker in colorectal cancer is worthy of further exploration, beyond tumours with MSI or POLE mutation." (PMID 30042065, 2018). "Germline mutations in POLE and POLD1 have been shown to cause predisposition to colorectal multiple polyposis and a wide range of neoplasms, early-onset colorectal cancer being the most prevalent." (PMID 28423643, 2017). "Mutations in POLE and POLD have been identified in kindred affected by colorectal cancer or polyposis, confirmed in multiple cohorts." (PMID 28492495, 2017). "We describe a strong mutation–methylation association across colorectal cancer subtypes, most interestingly in samples with microsatellite instability (MSI) or Polymerase epsilon (POLE) exonuclease domain mutations." (PMID 28531315, 2017). "Mutations in the proofreading domains of POLE and POLD1 were also reported in two human colorectal cancer cell lines (DLD-1 and LoVo) and 1/76 colorectal cancer patients, all three samples exhibiting MMR deficiency." (PMID 24705290, 2014). "No PV were found in other genes associated with colorectal cancer and/or polyposis, including POLE/POLD1 genes." (PMID 39031223, 2024). "Similarly, the genes encoding for the proofreading polymerases POLE and POLD1 displayed significantly higher mutation rates in CDX2-suppressed colorectal cancers." (PMID 39452477, 2024).
colorectal cancer (continued). "In the 37 brain tumor patients carrying rare POLE/POLD1 germline variants compiled here, gastrointestinal phenotypes were the most frequent additional features with colorectal adenomas in around 30%, and colorectal cancer in around 25% of cases." (PMID 37990341, 2023). "POLE somatic or germline mutations are found in many tumors, including non-melanoma skin cancer, endometrial cancer (EC), colorectal cancer (CRC), melanoma, bladder cancer, esophageal cancer, and lung cancer." (PMID 35780178, 2022). "Interestingly, these POLE mutations were predominantly associated with KRAS, NRAS, BRAF, and/or PIK3CA mutations, commonly found in colorectal cancers." (PMID 35624529, 2022). "Moreover, POLE/POLD1 variants carriers direct to associated phenotype characterized by attenuated or oligo-adenomatous colorectal polyposis, colorectal cancer, and brain tumors." (PMID 36685880, 2022). "In addition to MSI/MSS status, other biomarkers such as TMB, PDL1, POLE/POLD1 mutation, or MSI-like gene signature are also used in colorectal cancer." (PMID 34594218, 2021). "Germline pathogenic variants in the exonuclease domain (ED) of polymerases POLE and POLD1 predispose to adenomatous polyps, colorectal cancer (CRC), endometrial tumors, and other malignancies, and exhibit increased mutation rate and highly specific associated mutational signatures." (PMID 32792570, 2020). "Additionally, POLE and POLD1 somatic mutations can give rise to a Lynch syndrome‐like phenotype and microsatellite instable colorectal cancer." (PMID 30827058, 2019). "However, mutation burden not only strongly co-varied with MSI and POLE, but also provided prognostic information in MSI-negative colorectal cancers." (PMID 30042065, 2018). "Previously, it has been demonstrated that an endometrial or colorectal cancer harbouring POLE mutations without MSI induces immune-suppression through inhibition of the PD1/PD-L1 axis." (PMID 29880869, 2018). "We describe the association in detail within colorectal cancer subtypes, positing a potential role for MMR in the correction of deaminated 5mCs, and suggesting that Polymerase epsilon (POLE) exonuclease domain mutation increases mutagenesis specifically at 5mCs." (PMID 28531315, 2017). "Thus, driver mutations in colorectal cancers appear to purify in a manner that is independent of POLe." (PMID 40806338, 2025). "None of the class 2 and 3 BRAF-mutant colorectal cancers had pathogenic POLE mutations." (PMID 39751654, 2025). "In a similar reported case, in which a patient with a POLE frameshift germline variant presented mainly somatic MMRd-associated signatures, it could not be concluded whether the identified variant increased colorectal cancer predisposition." (PMID 36756361, 2023). "Moreover, the recent advances in molecular techniques, in particular Next-Generation Sequencing, have led to the identification of many new genes involved in the predisposition to colorectal cancers, such as RPS20, POLE, POLD1, AXIN2, NTHL1, MSH3, RNF43 and GREM1." (PMID 36768460, 2023). "As it is widely known that patients with MSI-H tumors can benefit from immunotherapy, routine clinical genetic testing for both POLD1/POLE and MSI-related mutations may help identify patients with endometrial and colorectal cancers who could respond well to immunotherapy." (PMID 36980791, 2023). "Other emerging biomarkers such as POLE/POLD1 and RET, though still in early validation phases, have expanded stratification and therapeutic approaches for colorectal cancer patients." (PMID 40308511, 2025).
colorectal cancer (continued). "Consistent with the idea that replication stress dictates CHKi response, silencing of multiple DNA polymerase isoforms, including POLA1, POLE, and POLE2, enhances replication stress and increases CHK1i sensitivity in lung and colorectal cancer cell lines." (PMID 35444937, 2022). "Hypermutation, both independent of and related to MSI-H or POLE mutant forms of colorectal cancer, was more common in patients with encapsulated liver metastases." (PMID 40702107, 2025). "This raises the question of whether POLE-mutant colorectal cancer also benefits less from adjuvant chemotherapy, similar to MSI-high colorectal cancer." (PMID 37239414, 2023). "Similarly to stomach cancer, we divided colorectal cancer by anatomical location (left versus right colon) and also based on the presence of MSI and POLE hypermutation, which have therapeutic relevance, yielding AUCs of 0.61 to 0.99." (PMID 30986244, 2019). "Although high mutation burden has been associated with good colorectal cancer prognosis in the context of MSI and POLE proofreading deficiency, this relation has not previously been shown for colorectal cancers without those forms of genomic instability." (PMID 30042065, 2018). "Similarly, DNA replication gene knockout may improve CHK1i activity, by inhibiting POLA1, POLE, and POLE2 genes in a siRNA screen performed on lung and colorectal cancer cells showing low sensitivity to CHK1i60." (PMID 38555285, 2024).
colon carcinoma (34 papers, 2014 to 2025). "Among MMR-associated genes, MSH6 and PMS2 were significantly more frequently mutated in CDX2-suppressed colon cancers, and the same was true for mutations in the proofreading polymerases POLE and POLD1 genes." (PMID 39452477, 2024). "This 45-year-old male had local recurrent colon cancer and liver metastasis with P286R and F1907L POLE mutations." (PMID 39218995, 2024). "It is known that compared to MSS colon cancer, colon cancer with mutations in the exonuclease domain in POLE has a higher mutational burden, higher expressions of immune checkpoints such as PD-L1, and a higher expression of T-cell markers." (PMID 37239414, 2023). "As such, we are among the first to present this POLE variant to be associated with an ultra-mutated phenotype in an otherwise MSS colon cancer subject receiving an immune checkpoint blockade." (PMID 37239414, 2023). "Our case distinguishes itself from others in the literature; however, we present a previously undescribed POLE variant mutation in the exonuclease proofreading domain in a subject with an MSS but ultra-mutated colon cancer treated with pembrolizumab." (PMID 37239414, 2023). "Mutations in the proofreading exonuclease domain in POLE lead to ultra-mutated colon cancer that is microsatellite stable." (PMID 37239414, 2023). "We describe a case where a patient with POLE-mutated and hypermutated recurrent colon cancer was treated with pembrolizumab." (PMID 37239414, 2023). "In colon cancer, about 7.4% of patients harbor POLE or POLD1 mutations, and most of this population was MSS or MSI-L." (PMID 36483562, 2022). "The primary sites for patients with POLE driver mutations were also different in the two cohorts, although there were more patients with left‐side colon cancer in both cohorts (Japanese research vs. Lancet pooling research: 68.10% vs. 57.40%)." (PMID 33125191, 2021). "All included patients with POLE driver mutations were relatively young (mean age <55 years old) and at an early stage of colon cancer (Stage 0–II >70.00%)." (PMID 33125191, 2021). "The human colon carcinoma cell line HT115 possesses a missense mutation in one copy of the DNA polymerase epsilon (POLE) gene, specifically a V411L mutation in the exonuclease domain which has been associated with hypermutated cancer phenotypes." (PMID 30459213, 2018). "When the samples with POLE mutation pattern are removed, the mutation pattern of the remaining colon cancer samples is very similar to most cancer types with a high proportion of mutations at CpG positions." (PMID 29673314, 2018). "We applied lineage sequencing to a human colon cancer cell line with a DNA polymerase epsilon (POLE) proofreading deficiency (HT115) and a human retinal epithelial cell line immortalized by constitutive telomerase expression (RPE1)." (PMID 30459213, 2018). "Five of those (and three of the other colon cancer samples) have a nonsynonymous mutation in POLE and one of them in addition in POLD1, which encodes the DNA polymerase δ." (PMID 29673314, 2018). "In summary, we have identified a unique subclass of colon cancer characterized by a hypermutation associated with the POLE mutation." (PMID 27612425, 2016). "For example, mutations in DNA polymerase epsilon (POLE) have been reported in endometrial and colon cancers with elevated numbers of somatic mutations, which appears to correlate with a robust intratumoral T-cell response and better prognosis." (PMID 27756408, 2016). "The overall evidence clearly suggests that extra-colonic cancers need to be taken into consideration in risk management and follow up of patients with POLE mutation." (PMID 25860647, 2015). "Exome sequencing of members of a family with high burden of colorectal adenomas and carcinomas, in addition to extra-colonic cancers, has identified the novel mutation c.1373A>T (p.Tyr458Phe) in POLE as a likely predisposing mutation." (PMID 25860647, 2015).